CXCL13 (C-X-C motif chemokine ligand 13)
Diseases named in the same sentence as CXCL13 in open-access papers (continued):
Sharing a sentence is not in itself a finding about the gene and the disease.
multiple sclerosis (continued). "CXCL13 is a key homeostatic chemokine constitutively expressed in lymphoid organs and also induced upon CNS inflammation, serving as a biomarker for Lyme neuroborreliosis (LNB), CNS lymphoma, and multiple sclerosis (MS)." (PMID 39636121, 2025). "Similar contributions of CXCL13 to the formation of ectopic lymphoid structures was later identified in Sjögren's syndrome, autoimmune thyroiditis, myasthenia gravis, systemic lupus erythematosis (SLE), and multiple sclerosis." (PMID 31354634, 2019). "The CSF milieu in multiple sclerosis has been intensively studied, and we could confirm a significant upregulation of CCL22 and CXCL13 in active MS patients." (PMID 31727097, 2019). "CSF CXCL13, APRIL, and BAFF levels have been shown to be elevated in autoimmune disorders, including anti-NMDA receptor encephalitis, opsoclonus myoclonus ataxia syndrome, NMO, multiple sclerosis and optic neuritis." (PMID 26919719, 2016). "CXCL13 neutralization had also a beneficial effect in mouse models for rheumatoid arthritis and multiple sclerosis, although the effect on TLO formation was not determined in this study." (PMID 27656182, 2016). "In addition, expression of CXCL13 was found in other non-lung disorders such as rheumatoid arthritis and multiple sclerosis, which further confirmed that CXCL13 is contributed to the development of chronic inflammatory diseases." (PMID 35165593, 2022). "In contrast to the authors' findings, in our studies including both non-inflammatory neurological disorders (NIND; n = 62) and multiple sclerosis (MS) patients we observed a significant correlation between serum CXCL13 concentrations and CSF CXCL13 concentrations." (PMID 33632258, 2021). "Elevated CSF CXCL13 levels have also been found in patients with HIV, Cryptococcus neoformans meningitis, congenital toxoplasmosis, viral encephalitis, viral meningitis (e.g., varicella zoster virus, herpes simplex virus, and tick-borne encephalitis virus), multiple sclerosis, and CNS lymphoma." (PMID 34132584, 2021). "Furthermore, this mouse anti-CXCL13 antibody demonstrated efficacy in a mouse model of Rheumatoid arthritis (Collagen-Induced Arthritis (CIA)) and Th17-mediated murine model of Multiple Sclerosis (passively-induced Experimental Autoimmune Encephalomyelitis (EAE))." (PMID 25879435, 2015).
Lyme neuroborreliosis (63 papers, 2009 to 2026). "In patients with humoral immunity deficiency and symptoms suggestive of neuroborreliosis, tests for CXCL13 should be performed on CSF samples because high specificity and sensitivity, compared with PCR, makes this test a valuable diagnostic tool." (PMID 39983686, 2025). "Of these, the B cell chemokine Cxcl13 has become of particular interest due to its strong association with Lyme neuroborreliosis compared to healthy controls and patients with other neuroinflammatory diseases." (PMID 33524035, 2021). "When spirochetes of Borrelia burgdorferi, the causative organism of Lyme disease, invade the CNS, spirochetal lipoproteins induce the release of CXCL13 into the CSF by resident mononuclear cells." (PMID 32419252, 2020). "We described that neuroborreliosis and neurosyphilis are associated with an elevated CXCL13 concentration, mainly in the cerebrospinal fluid." (PMID 32331231, 2020). "CXCL13 also confirmed the diagnosis of possible neuroborreliosis in 100% of patients, indicating a higher diagnostic sensitivity than intrathecal-specific antibodies synthesis." (PMID 32331231, 2020). "Because of the fact that one of the key regulators of B-cells is chemokine CXCL13, a number of research papers evaluating the diagnostic significance of CXCL13 in patients with neuroborreliosis and neurosyphilis were presented in this review." (PMID 32331231, 2020). "The third issue is that although CXCL-13 appears to be a good alternative diagnostic test for the diagnosis of early Lyme neuroborreliosis, it has yet to be assessed in late Lyme neuroborreliosis." (PMID 32509603, 2020). "Similar to neuroborreliosis, CXCL13 has been implicated in the pathogenesis of neurosyphilis, a serious complication of untreated syphilis." (PMID 31354634, 2019). "By using a set of markers in addition to CXCL13 and IL-17A, we confirm that B cell- and Th17-associated immune responses are involved in Lyme neuroborreliosis pathogenesis with different patterns in subgroups." (PMID 28148307, 2017). "The chemokine CXCL13 has been discussed as a diagnostic parameter with high specificity for Lyme neuroborreliosis (LNB) and as a marker of disease activity." (PMID 25975424, 2015). "It has been suggested that cerebrospinal fluid (CSF) CXCL13 is a diagnostic marker of Lyme neuroborreliosis (LNB), as its levels have been shown to be significantly higher in LNB than in several other CNS infections." (PMID 23294475, 2013). "A recent retrospective cross-sectional study that included 1234 patients undergoing a lumbar puncture demonstrated the highest diagnostic performance of CSF CXCL13 concentration as an activity marker for acute neuroborreliosis (92.1% sensitivity, 96.5% specificity)." (PMID 38674602, 2024). "C-X-C-motif chemokine ligand 13 (CXCL13) in cerebrospinal fluid (CSF) is increasingly used in clinical routines, although its diagnostic specificity and divergent cut-off values have been defined so far mainly for neuroborreliosis." (PMID 38203597, 2023). "Moreover, research studies on the diagnostic significance of CXCL13 in neuroborreliosis and neurosyphilis were performed on relatively small, heterogeneous cohorts." (PMID 32331231, 2020). "Based on these published findings, we suggest that CXCL13 determination in CSF improves the sensitivity of neuroborreliosis and neurosyphilis diagnostic tests, and supports the implementation of CXCL13 determination in routine laboratory diagnostics for both infectious diseases." (PMID 32331231, 2020). "Combining CXCL13 with other diagnostic markers for neuroborreliosis has produced promising results." (PMID 32331231, 2020). "Indeed, CSF CXCL13 level has been proposed as a diagnostic biomarker for neuroborreliosis, and a recent meta-review of 18 studies calculated a pooled sensitivity and specificity of 89 and 96%, respectively, for CNS CXCL13 as a biomarker of disease." (PMID 31354634, 2019).
Lyme neuroborreliosis (continued). "It has also been suggested that CXCL13 could be a diagnostic marker of Lyme neuroborreliosis and rheumatoid arthritis." (PMID 25789329, 2015). "Based on the observation that high CXCL13 levels are found in the CSF of patients with acute neuroborreliosis, CXCL13 was proposed as a specific diagnostic marker and a key regulator for B cells in acute Lyme neuroborreliosis." (PMID 22591862, 2012). "Production of CXCL13 by infiltrating microglia and macrophages/DC myeloid cells was found in the model of neuroborreliosis in the macaque Rhesus." (PMID 40165834, 2025). "CXCL13 can be determined in CSF when early Lyme neuroborreliosis is clinically suspected and the CSF cell count and/or Borrelia-specific AI are (still) inconspicuous." (PMID 41195425, 2025). "CXCL13 is a B cell chemoattractant, which has been identified as a potential biomarker for Lyme neuroborreliosis in cerebrospinal fluid (CSF)." (PMID 40576342, 2025). "High CSF CXCL13 levels have also been observed in other neurological conditions, including autoimmune encephalitis, paraneoplastic syndromes, active neuroborreliosis, and neurosyphilis." (PMID 39857624, 2024). "Elevated CXCL13 levels were found in the cerebrospinal fluid (CSF) of patients with MS, neuroborreliosis and other inflammatory neurological diseases." (PMID 38691538, 2024). "Cerebrospinal pleiocytosis, intrathecal antibody production of IgM and IgG isotypes, and an increased level of CXCL-13 in the cerebrospinal fluid are typically present in patients with neuroborreliosis." (PMID 37240779, 2023). "In our experience, apart from neurosyphilis CXCL13 >5000 pg/ml is only seen in neuroborreliosis, cryptococcosis, and carcinomatous meningitis or CNS lymphoma, and these differential diagnoses have been ruled out in all three patients." (PMID 37868301, 2023). "CXCL13 has been found to be upregulated in the CSF of patients with spirochaetal neuroinflammation related to neuroborreliosis and neurosyphilis." (PMID 38983560, 2022). "The chemokine CXCL13 is used as complement to serology in the diagnostics of Lyme neuroborreliosis (LNB)." (PMID 34626256, 2022). "The CXCL13 levels in the CSF of patients with neurosyphilis exceeded 250 pg/ml and was second only to the concentrations found in patients with neuroborreliosis." (PMID 38983560, 2022). "CXCL13 is also a key regulator of B cell recruitment to the cerebrospinal fluid in acute Lyme neuroborreliosis." (PMID 34947813, 2021). "The studies have mainly examined patients with possible neuroborreliosis for which an increased CXCL13 level was found in 73% of cases." (PMID 34200467, 2021). "CXCL13 seems to be a potential candidate as a biomarker for diagnosis and control of treatment success in neuroborreliosis." (PMID 34573864, 2021). "The investigation of CXCL13 in patients with clinically suspected neuroborreliosis but an antibody index below 2 would be of great interest." (PMID 34573864, 2021). "Recent studies have shown elevated levels of the B-cell chemokine (C-X-C motif) ligand 13 (CXCL13) in the cerebrospinal fluid (CSF) of patients with early Lyme neuroborreliosis (LNB)." (PMID 34132584, 2021). "The use of chemokine (C–X–C motif) ligand 13 (CXCL13), a B-cell attracting chemokine, was debated for the laboratory diagnosis of acute Lyme neuroborreliosis in CSF." (PMID 32793606, 2020). "In recent years, the chemokine CXCL13 has been shown to increase significantly in the CSF of almost all patients with acute Lyme neuroborreliosis – even before a specific antibody response is generated." (PMID 32341686, 2020). "All children with possible neuroborreliosis, pleocytosis, facial nerve palsy, and/or anti-Borrelia burgdorferi sensu lato antibodies have been found to have increased levels of CXCL13 in the CSF." (PMID 32331231, 2020).
Lyme neuroborreliosis (continued). "B cells are then recruited to the infectious site by a concentration gradient of CXCL13, and CXCL13 also facilitates B‐cell differentiation into plasma cells, inducing pleocytosis in the CSF of patients with neuroborreliosis." (PMID 32419252, 2020). "One study revealed that differences in CXCL13 levels between children with neuroborreliosis and those with other conditions were statistically significant, although relatively small." (PMID 32331231, 2020). "In regard to CSF CXCL13 concentration and its usefulness in differentiating between neurosyphilis and neuroborreliosis, data are inconsistent." (PMID 32331231, 2020). "Similar to neuroborreliosis, CSF levels of CXCL13 have been proposed as a biomarker for neurosyphilis with a sensitivity and specificity of 85 and 89%, respectively, with the highest diagnostic value being in HIV-infected patients." (PMID 31354634, 2019). "B cell immunity, including the chemokine CXCL13, has an established role in Lyme neuroborreliosis, and also, T helper (Th) 17 immunity, including IL-17A, has recently been implicated." (PMID 28148307, 2017). "The chemokine CXCL13 has been evaluated as a possible CSF biomarker for detection of acute neuroborreliosis." (PMID 28109263, 2017). "Elevated CSF CXCL13 concentration has been shown to be a good marker for active Lyme neuroborreliosis." (PMID 27376011, 2016). "The proposed cut-off for abnormal CSF CXCL13 was low in comparison to similar studies regarding neuroborreliosis." (PMID 27376011, 2016). "Elevated CXCL13 levels were found in the CSF of patients with MS, neuroborreliosis and other inflammatory neurological diseases." (PMID 22591862, 2012). "In the subgroup of OIND patients, highest CSF CXCL13 levels were similar to those observed in patients with acute Lyme disease." (PMID 22591862, 2012). "CXCL13 is no disease-specific marker of MS or CIS: Particularly high concentrations of CSF CXCL13 can be found in patients with neuroborreliosis, which is the neuroinflammatory disease with the highest proportion of B cells in the CSF." (PMID 20700489, 2010). "Recently, we and others observed a strong up-regulation of CXCL13 expression in an acute bacterial infection, in Lyme neuroborreliosis (LNB)." (PMID 20042073, 2009). "Cytokine-mediated inflammation, especially CXCL13 elevation, correlates with disease activity and may serve as a biomarker of active neuroborreliosis." (PMID 41487709, 2025). "Recently it has been shown that chemokine CXCL13 levels increase significantly in the CSF of almost every patient with acute Lyme neuroborreliosis – even before a specific antibody response has been generated (if symptoms last <6 weeks, the Borrelia-specific AI can be negative in 10–30% of cases)." (PMID 41195425, 2025). "CXCL13 is well known and elevated in neuroborreliosis and neurosyphilis." (PMID 41366113, 2025). "High intrathecal CXCL13 levels strongly indicated neuroborreliosis, a hypothesis confirmed by CSF PCR positivity for B. spielmanii despite negative results of serologic testing for Borrelia." (PMID 39983686, 2025). "Since CXCL13 was first described as a B-cell-attracting chemokine in 1998, there has been much debate as to whether it can serve as a biomarker in neuroborreliosis." (PMID 38203597, 2023). "In the meantime, there is a large number of studies on CXCL13, mainly in neuroborreliosis but also to a lesser extent in various other infectious, autoimmune, and malignant neurological diseases with different study populations, diseases, and detected cut-offs for CSF-CXCL13." (PMID 38203597, 2023). "However, elevated CSF levels of CXCL13 have been described for certain neuroinfectious conditions such as neuroborreliosis and neurosyphilis." (PMID 33841320, 2021). "One of the key regulators of B-cells is CXCL13, whose concentration may be elevated at the onset of neuroborreliosis, before the synthesis of intrathecal Borrelia burgdorferi sensu lato antibodies occurs." (PMID 32331231, 2020).
Lyme neuroborreliosis (continued). "Moreover, literature data suggest that CXCL13 determination is the most interesting additional marker for diagnosis and monitoring of neuroborreliosis and neurosyphilis thanks to its high sensitivity." (PMID 32331231, 2020). "Furthermore, the role of the chemokine CXCL13, also known as B‐cell‐attracting chemokine‐1, which is important for B‐ and T‐cell homing, in Lyme neuroborreliosis, can yield insight into that in neurosyphilis." (PMID 32419252, 2020). "New two-tier testing strategies using two ELISA tests (C6 and WCS for example) to replace immunoblot are currently proposed by some authors and guidelines, and promising new tests such as CXCL-13 in CSF are promising tools for the improvement of the diagnosis of Lyme borreliosis." (PMID 32509603, 2020). "Moreover, it has been proven that CSF levels of CXCL13 are significantly increased in patients with definite acute neuroborreliosis, possible neuroborreliosis with pleocytosis, and possible neuroborreliosis with positive specific antibodies." (PMID 32331231, 2020). "CXCL13 is overexpressed within the muscles of monkeys chronically infected with Borrelia burgdorferi (the etiological agent of Lyme disease), and CXCL13 was later shown to contribute to the formation of ectopic germinal centers within the central nervous system." (PMID 31354634, 2019). "The chemokine CXCL13 is an intensively investigated biomarker in Lyme neuroborreliosis (LNB)." (PMID 30660201, 2019). "Lyme disease has been associated with the proinflammatory cytokines Interleukin-6, Interleukin-8, Interleukin-12, Interleukin-18 and interferon-gamma; the chemokines CXCL12, CXCL13 and CCL19 and increased levels of proinflammatory lipoproteins." (PMID 30149626, 2018). "CXCL13 analysis might help in such cases to differentiate between acute neuroborreliosis and previous infection." (PMID 28109263, 2017). "These may be the reason why the elevated CSF CXCL13 levels in neurosyphilis patients were lower than in neuroborreliosis patients." (PMID 27376011, 2016). "CXCL13 is expressed at high levels in the CSF of patients with Lyme neuroborreliosis (LNB)." (PMID 25975424, 2015). "Notably, CSF levels of CXCL13 were found to be 100-fold higher in patients infected with Treponema pallidum (the etiological agent of syphilis) than in uninfected individuals, although approximately four times lower than individuals with neuroborreliosis." (PMID 31354634, 2019). "In Lyme neuroborreliosis (LNB), where CXCL13 production is robust, CXCL13 was shown to be produced by myeloid and plasmacytoid dendritic cells." (PMID 39766248, 2024). "The pooled CSF CXCL-13 sensitivity ranged from 89 to 97% and its pooled specificity was 96% (CI95% = 92–98%) in two meta-analyses (961 patients presenting Lyme neuroborreliosis and 3,282 controls)." (PMID 32509603, 2020). "Previous work has shown an increase in the cerebrospinal fluid (CSF) in subjects with Lyme neuroborreliosis where CXCL19, along with CXCL13, is proposed to play a role in B cell recruitment." (PMID 24740099, 2014). "Patients with CIS, MS, Lyme disease and OIND all showed higher CSF CXCL13 levels than patients with NIND (P <0.001, P <0.01, P <0.001 and P <0.001 respectively)." (PMID 22591862, 2012). "It should be noted that the CXCL13 value is not specific to Lyme neuroborreliosis; elevated CSF values have also been found in neurosyphilis, tuberculous meningitis and CNS lymphomas." (PMID 41195425, 2025). "Although chemokine ligand 13 (CXCL13) is a recognized biomarker for acute neuroborreliosis, there are no specific biological markers for PSL, making it extremely difficult to define the disease." (PMID 37240779, 2023). "Intriguingly, overexpression of CXCL13 was detected in the muscles of monkeys chronically infected with the Lyme disease pathogen Borrelia burgdorferi, but the bacterium did not appear to have an effect on plasma levels of CXCL13 chemokines." (PMID 35702353, 2022).